CXCL10 (C-X-C motif chemokine ligand 10)
Diseases named in the same sentence as CXCL10 in open-access papers (continued):
Sharing a sentence is not in itself a finding about the gene and the disease.
tumor (continued). "Our findings affirm that isiBCL-2 molecules effectively stimulate the upregulation of IFN-β, CXCL10, and MHC-I levels in tumor cells via the RIG-I signaling pathway, promoting immune system activation and reversing the immunosuppressive tumor microenvironment." (PMID 38685028, 2024). "Chemotherapeutic treatment of tumor-bearing mice was reported to lead to intratumoral expression of CXCL9, CXCL10, and CCL5 chemokines which facilitate recruitment and infiltration of CD4+ and CD8+ T cells into the tumor bed." (PMID 38360737, 2024). "The CXCL9, CXCL10, and CXCL11-CXCR3 axes are reported to regulate cytotoxic lymphocyte migration and mediate a tumor suppression response." (PMID 39076974, 2024). "These core genes contained at least 8 (PPP2R2A, CXCL10, CXCL11, GBP1, IRF1, RARRES3, STAT1, and TAP1) previously identified regulators of tumor progression and distant metastasis." (PMID 38545852, 2024). "Our results showed that PARP/HDACi treatment augmented the mRNA levels of CCL5 and CXCL10 in three different TNBC cell lines and MDA-MB-436 tumor-bearing mice." (PMID 38182579, 2024). "In tumor regions, the expression levels of CCL2, CCL5, CCL20, CXCL9, CXCL10, CXCL11 and CXCL12 were generally higher in hot tumors than in the other two groups." (PMID 37847338, 2024). "IFNγ induces macrophages to produce more CXCL9 and CXCL10, two chemokines that bind to CXCR3 on the surface of T cells and promote their recruitment for anti-tumor immune response." (PMID 38787372, 2024). "In gastric cancer, a high level of TG2 activity enhanced inflammation and tumor growth by recruiting macrophages to the tumor via the IL-1β-mediated induction of CCL2 and CXCL10." (PMID 38474044, 2024). "By RT-qPCR, we revalidated the expression of CXCLs (CXCL2, CXCL3, CXCL5, CXCL10) in MB49 YAP1-Sh clones and tumor tissues from VP-treated mice bearing UCB cell–derived xenografts." (PMID 39630608, 2024). "In HCC, SASP components, including IL‐6, IL‐8, CXCL10 and AREG, foster angiogenesis, while overexpression of DNASE1L3 inhibits tumour angiogenesis by disrupting the SASP in response to DNA damage stress." (PMID 39270064, 2024). "Other identified biomarkers in the pretreated tumor microenvironment in this trial include CXCL9, CXCL10, CD8, and 12-chemokine signatures and tertiary lymphoid structures." (PMID 38540132, 2024). "Some chemokines play important roles in recruiting immune cells, such as CXCL9 and CXCL10, which can recruit NK cells, NKT cells, and macrophages to the TME and increases the cytotoxic activity against tumor cells." (PMID 39139561, 2024). "This is supported by our analysis showing a correlation between high IDO1 and high CXCL10; the latter IFN-γ-related chemokine has a pivotal influence on cytotoxic T cell tumor recruitment and ICI response." (PMID 38632994, 2024). "Our findings also indicate that IFNα and CXCL10 recruit and activate CD8+ T cells toward the tumor cells, potentially transforming “cold tumors” into “hot tumors” that are more responsive to immunotherapy." (PMID 38953994, 2024). "Dendritic cells must reach the tumour first in order to generate chemokines, such as CXCL9 and CXCL10, which recruit effector T cells to the tumour, resulting in tumour control." (PMID 38481668, 2024). "The resulting pro-inflammatory milieu significantly suppresses prostate tumor growth, an effect diminished when IFN-γ and CXCL10 pathways are inhibited, highlighting SIRT1’s role in immune-mediated tumor suppression." (PMID 39796040, 2024). "In 2021, Thomas F Gajewski and colleagues reported that up to 90% of PTPRC+ cells produced CXCL10 transcripts, which played a critical role in recruiting effector CD8+ T cells to the tumor site." (PMID 38571962, 2024). "It is, therefore, possible that the effect of CXCL10-Fc on NK cells is indirect and is in response to the high levels of IFN-γ, IL-2, and other cytokines at the tumor site." (PMID 39474427, 2024).
tumor (continued). "Investigations revealed that heightened CXCL10 expression impedes tumor proliferation while enhancing CD8+ T cell penetration, thereby facilitating the normalization of tumor vasculature." (PMID 39170612, 2024). "Tumor-resident cDC1s are crucial for regulating the trafficking of effector T cells to the TME through the secretion of CXCL9 and CXCL10, suggesting that cDC1-T-cell crosstalk is also evident at tumor sites." (PMID 36949244, 2023). "The secreted CXCL9, CXCL10 and CXCL11 interact with tumour cells to induce cell death, such as apoptosis and attract adaptive immune cells leading to anti‐tumour immunity." (PMID 37170733, 2023). "Consistently, tumor tissues in IDO1 overexpression and CXCL10 knockdown groups showed high and low expression of KI67, respectively." (PMID 37903782, 2023). "OV-mediated ICD triggers the release of IL-6, IL-8, IFN-β, IP-10 (CXCL10), MCP-1 (CCL2) and KC (CXCL1) from cancer cells to recruit different immune cells and initiate an anti-tumor response." (PMID 36831636, 2023). "An ongoing trial (NCT04053283) is assessing a tumor-selective vector expressing a FAP-T cell activator bispecific antibody, which also expresses CXCL9, CXCL10, and IFN-a in multiple epithelial cancers, and preliminary data showed no toxicity." (PMID 37754534, 2023). "Previous studies have shown that chemokines CXCL9 and CXCL10 can recruit CD8+ T cells, Th1 cells and NK cells by recognizing CXCR3 signals, thus triggering anti-tumor response." (PMID 37950246, 2023). "The production of CXCL10 in urine during BCG treatment has been previously confirmed, and CXCL10 has been shown to play a key role in eliciting anti-tumor immune reactions." (PMID 38002062, 2023). "The four GEO datasets and our clinical samples confirmed that the expression levels of CXCL10, IDO1, and MAB21L2 were significantly higher in tumor tissues than in control tissues (P < 0.05)." (PMID 37596528, 2023). "Prior reports have shown that IFN-β, CXCL10, and CCL2 are increased after ATRi plus RT in the TME and in tumor cells cultured in vitro, and this has been attributed to tumor cell–intrinsic signaling." (PMID 36810257, 2023). "This immunomodulatory effect was not restricted to oxaliplatin, other platinum-based drugs, such as carboplatin, have also increased tumor CD8+ T cell populations and enhanced CCL5 and CXCL10 mRNA levels in lung cancer cells." (PMID 36949946, 2023). "cGAMP production and export by tumour cells can activated STING signalling in neighbouring endothelial cells, to induce further IFN-β and CXCL10 production in the TME." (PMID 37534795, 2023). "Treg cells are mainly recruited to the tumor microenvironment by chemokines such as CCL1, CCL17, CCL22, CCL28, CXCL9, CXCL10, and CXCL11." (PMID 37686093, 2023). "In the context of cancer, autophagy inhibition is reported to enhance immune cell tumor infiltration by increasing the secretion of pro-inflammatory IFNγ and C–C motif ligand (CCL)-5 (alias RANTES) and CXCL10 chemokine in melanoma, CRC and GBM murine models." (PMID 38071322, 2023). "In this regard, we provide compelling evidences that THBS1-CXCL9/CXCL10 axis plays critical roles in CD8+ T cells recruitment and subsequent anti-tumor immunity." (PMID 37853469, 2023). "The first study of note is an attempt by Liu and colleagues who noted KRAS-G12D mutation responsible for suppressing the PD-L1 targeted therapy and CXCL10/CXCL11 (chemokines) secretion, together suppressing the CD8+ tumor infiltrating lymphocytes (TILs)." (PMID 37970206, 2023). "We then constructed the tumor model by symmetrically injecting the MC38 cells subcutaneously into the bilateral flanks of wild-type and CXCL10 knockout mice according to our previous study." (PMID 36900218, 2023). "In the treated group, the LIVP-RFP cytokine analysis suggested elevation of CXCL10 in the tumor samples and IFN-α, IFN-γ, CCL2, CCL3, CXCL9, and CXCL10 in the sera samples." (PMID 37112810, 2023).
tumor (continued). "N1 subtype secretes CCL3, CCL9, CXCL10, TNF-α, IL12, Cathepsin G, and neutrophil elastase (NE) to recruit, activate and induce proliferation of T-cells to implement anti-tumor influence and improve adaptive immune responses." (PMID 37376417, 2023). "IP-10 (CXCL10) is a well-known chemoattractant that increases the expression of interferon genes and promotes effector CD8+ and NK tumor infiltration." (PMID 37627156, 2023). "CXCL10 and CCL5 chemokines were reported to stimulate CD4+ and CD8+ lymphocyte migration into the intra-tumor and stromal compartment, and CCL20 drove brain infiltration of Treg cells." (PMID 38239560, 2023). "ThyroidPrint® is a novel q-PCR-based ten-gene classifier with its signature representing both the tumor microenvironment (CXCR3, CXCL10, CCR3, CCR7, and CXADR) and tumor epithelial cells (TIMP1, CLDN1, KTR19, AFAPL2, and HMOX1)." (PMID 37671897, 2023). "Adoptive transfer of human γ∂-T cells primed with zoledronic acid induced MHC-I expression and CXCL10 levels in the TME and reduced tumor growth, leading to increased overall survival in xenografts of SH-SY5Y human NBL cells in female athymic nude Balb/c mice." (PMID 37426669, 2023). "Our results were consistent with the notion that the anti-tumor immune response elicited by ICB requires the involvement of macrophage-derived CXCL9 and CXCL10." (PMID 36900218, 2023). "CXCL9, CXCL10, and CXCL11 are ligands of CXCR3 and have been increasingly recognized as key regulators of the tumor microenvironment." (PMID 37686653, 2023). "In this study, we established SCCVII cells stably expressing the IFN-inducible chemokines CXCL9, CXCL10, and CXCL11 and transplanted the cells into the backs of nude mice to investigate their anti-tumor effects." (PMID 37218983, 2023). "CXCR3/CXCL9/CXCL10/CXCL11 axis leads to recruitment of tumor-promoting immune cells, including TAMs, T cells, etc., thus favoring tumor growth and metastasis." (PMID 37818357, 2023). "Lastly, molecular analyses show that the communication between BC cells and CAFs is dependent on physical interactions, deriving in the production of soluble factors involved in tumour cell survival and proliferation such as RANTES, ICAM1, and CXCL10." (PMID 36949770, 2023). "As detected by qPCR, significantly increased mRNA expression levels of CXCL1, CXCL2, CCL5, CXCL10, and IFN-β were detected in tumor tissues isolated from the shIDH3α + CDDP + PD-L1 group compared to the control+CDDP+PD-L1 and shIDH3α groups." (PMID 36980689, 2023). "Ablation of USP15 increases TET2 binding to Cxcl9, Cxcl10, and Cxcl11 promoters, which trigger the production of IFN-γ chemokines and boosts tumor-infiltrating lymphocytes to improve the responsiveness to anti-PD-L1 treatment." (PMID 37658402, 2023). "Western blot data also indicated that cytokines content in the tumor was remarkably increased after combined therapy compared with other groups, including IL-12, IFN-γ, CXCL-9, and CXCL-10." (PMID 37391451, 2023). "We made similar observations for Stat1 and other STAT1 target genes including Irf1, Cxcl10, and Cxcl11, which suggested that PARP14 was induced specifically in IFNγ-inflamed tumours but independently of α-PD-1." (PMID 37752135, 2023). "IFN-β, IL-6, CXCL10, CCL2, and CCL5 have been reported to be induced in tumor cells by ATRi plus RT in vivo and/or in vitro." (PMID 36810257, 2023). "By inhibiting the recruitment of EZH2 on the CXCL10 promoter, knockdown of HDAC-10 can promote the increase of CXCL10 expression in HCC, inducing the recruitment of T cells and NK cells, and regulating and controlling the anti-tumor response in the TME." (PMID 37304265, 2023). "STING signaling also generates a chemokine gradient, including CXCL10, CCL5, and CXCL9, that can guide the recruitment and activation of T cells and NK cells within the tumor." (PMID 37627155, 2023).
tumor (continued). "Since we observed differences in Cxcl9/Cxcl10 staining in KPC2 vs. KPC2a tumors, we next tested if there were tumor cell intrinsic differences in chemokine expression by KPC2 and KPC2a cells." (PMID 36472588, 2023). "CXCL9 and CXCL10 can recruited TH1 cells and NK cells into the tumors and played a role in tumor inhibition." (PMID 38125697, 2023). "Our recent report demonstrated that CXCL10, the increased inflammatory cytokine resulted from liver graft injury, recruited MDSCs into liver graft through TLR4/MMP9 to promote tumor recurrence post transplantation." (PMID 37175922, 2023). "CXCL9 and CXCL10 through their receptor CXCR3 regulate immune cell migration, differentiation, and activation, leading to tumor suppression under some conditions." (PMID 37296899, 2023). "Intratumor microbiota such as Lachnoclostridium genus, Gelidibacter, Flammeovirga, and Acinetobacter induce tumor cells to secrete chemokines CXCL9, CXCL10, and CCL5, thereby recruiting CD8+ T cell infiltration." (PMID 37937304, 2023). "Partial neutrophil depletion using an anti-Ly6G antibody suppressed the upregulation of CXCL10 and MHC class II in neutrophils and reversed the anti-tumor activity of BCG in mouse models." (PMID 38002062, 2023). "Previous humanized mouse studies indicated that intratumoral injection of CAdVEC induced expression of chemokines CXCL10 and CCL5 at tumor sites." (PMID 36989357, 2023). "The addition of TIGIT blockade to MWA resulted in the up-regulation of CXCL9 and CXCL10 expression in TAMs and their receptor CXCR3 expression in T cells, which restrain tumor growth and enhance anti-tumor immunity." (PMID 36900218, 2023). "Pre-treatment with oxaliplatin and cyclophosphamide induced a pro-inflammatory tumor microenvironment and enhanced secretion of CCL5, CXCL9, CXCL10, and CXCL16 by tumor-infiltrating macrophages, leading to enhanced ROR1-CAR-T cell infiltration." (PMID 36949946, 2023). "Th17 cells promote tumor immunity via the induction of CXCL9 and CXCL10, key chemokines that promote the infiltration and activation of cytotoxic NK cells and CD8+ T cells within the TIM." (PMID 37766141, 2023). "Direct injection of BATF3 DCs into the tumor region restored CXCL9 and CXCL10 expression and T-cell infiltration in WNT signaling pathway-positive tumors." (PMID 37546397, 2023). "Within the tumor, Batf3-dependent cDC1s that express CXCL9 and CXCL10 are required for effector T cell chemo-taxis." (PMID 37377970, 2023). "M1 macrophages exhibit enhanced antigen-presenting activity while secreting CXCR3 ligands (CXCL9, CXCL10, CXCL11) and CXCL16 to recruit Th1 and NK cells and secrete TNF-α, synergistically exerting anti-tumor functions." (PMID 37063892, 2023). "Natural killer (NK) cells and Th1 cells share CXCR3 receptors and exert anti-tumor effects in response to stimulation by the specific ligands CXCL9, CXCL10, and CXCL11." (PMID 37063892, 2023). "IP-10 (CXCL10) is an IFN-γ-induced protein belonging to the CXC chemokine family, which is able to reduce tumor growth, regulate angiogenesis, and increase the recruitment of cytolytic lymphocytes into tumor lesions." (PMID 37849764, 2023). "CXCL9, CXCL10, and CXCL11 were expressed most prominently by cluster 11, which was annotated as CD14(+) monocytes derived from neoplasms." (PMID 37686653, 2023). "M1-like macrophages penetrate the TME during the early phase of tumor by antigen presentation and secreting CXCL9, CXCL10, and CXCL11, which chemoattract CXCR3-expressing effector immune cells like CD8+ cytotoxic T cells and NK cells." (PMID 38035101, 2023). "NLRC3 showed moderate and strong correlations with CCL5, CXCL9, CXCL10, CXCL11, CXCR3, and CCR5, resulting in an increased recruitment of NK cells, TH1 cells, and CD8+ T cells in tumor tissues." (PMID 36808166, 2023). "Meanwhile, autocrine IFNs mediated CXCL10 and ICAM-1 expression in RT-treated tumors, which is potential to enhance LFA-1-ICAM-1 interaction for further activating anti-tumor CD8+ T cells." (PMID 36688994, 2023).
tumor (continued). "CXCL10 promotes the migration of CXCR3 expressing cells, such as T cells, monocytes, NK cells, and tumor cells." (PMID 37901214, 2023). "Radiation therapy plays a role in promoting the migration of effector T lymphocytes to the tumor site by inducing the expression and release of chemokines, such as CXCL-10 and CXCL-16, from tumor cells." (PMID 37511431, 2023). "Low passage tumor alone secreted high concentrations of CCL2/MCP1, CXCL8/IL-8, CXCL1/GRO, IL-6, CXCL10/IP10, G-CSF, TGFβ1, MMP1, CCL3/MIPα, GM-CSF and EGF." (PMID 37063842, 2023). "Pancreatic stellate cells in PAAD can secrete CXCL10, which can recruit CXCR3+CD4+ cells, CXCR3+CD8+ cells and CXCR3+ Tregs into tumor tissue." (PMID 36782176, 2023). "In PAAD, sensory-neuron-derived mediators CXCL10 and CCL21 pass through complementary receptors CXCR3 and CCR7 on tumor cells, activating AKT, MEK, and RAC signaling pathways in tumor cells to mediate migration." (PMID 36900158, 2023). "Eosinophil commitment to Th1 response was previously shown as well where these leukocytes produced CXCL9, CXCL10, CXCL11, and CCL5 under the effect of TNF-α and IFN-γ, which recruit T and NK cells to eradicate tumor." (PMID 37587450, 2023). "These DCs, along with macrophages and tumor cells, secrete chemokines like CXCL9 and CXCL10, which aid in recruiting circulating CXCR3-expressing CD8+ T cells to the tumor site to exert cytotoxic effects on tumor cells." (PMID 37920470, 2023). "Accumulation of NK cells within the tumors contributed to slowed tumor growth and augmented T cell infiltration through induction of CXCL9 and CXCL10 via NK cell-derived IFN-γ." (PMID 38022679, 2023). "Namely, epigenetic reprogramming of chemokine expression has been reported upon treatment with DNMTi, EZH2i and LSD1, increasing tumor production of CXCL9 and CXCL10 chemokines, known to be involved in T cell recruitment to the tumor." (PMID 37090711, 2023). "The CXCL10/CXCR3 axis has therapeutic potential by regulating angiogenesis, recruiting activated immune cells, and influencing the development of tumor cells, which in turn affects the TME." (PMID 37503314, 2023). "In parallel, circMET and circ_0020710 contribute to T cell exhaustion by upregulating CXCL10 and CXCL12 respectively via sponging tumor suppressive miRNAs." (PMID 38044445, 2023). "In fact, RT sustains CD8 T-cell recruitment into the tumor by inducing the expression of several factors, including IFNα, CXCL9, CXCL10, and CXCL11, as well as promoting extravasation by upregulating ICAM-1 and E-selectin on endothelial cells." (PMID 36831435, 2023). "Compared with SC144 treatment, SC144@HABN treatment significantly elevated the serum concentrations of HMGB-1 and CXCL-10 (p < 0.05) and increased CRT levels in CD45- tumor cells (p < 0.001)." (PMID 37553327, 2023). "Subsequently, IL-25 activates M2 macrophages in the TME and increases the secretion of C-X-C motif chemokine ligand 10 (CXCL10), which promotes the infiltration of CD8+ T cells in the TME and tumor development." (PMID 36950522, 2023). "Upregulation of several chemokines, including CCL3, CCL5, CCL22, CXCL9, CXCL10, and CXCL11, has been described to play different roles with effects depending on tumor type and other TME factors." (PMID 36831435, 2023). "Knockout or inhibition of CXCL10/TLR4 significantly reduced the M-MDSC levels and constrained tumor growth in a mouse recurrent tumor model." (PMID 36911674, 2023). "Chemo-taxis of effector T cells to the tumor depends on the expression of CXCR3 on T cells and the presence of its ligands, CXCL9, CXCL10, and CXCL11 within the TIME." (PMID 37377970, 2023). "CXCL10, P2RX7, TLR3, and TLR4 were significantly upregulated in IS2 tumours in the TCGA cohort, whereas ANXA1, CXCL10, FPR1, IFNAR2, P2RX7, and TLR4 showed significantly higher expression levels in IS4 tumours in the GEO cohort." (PMID 36851274, 2023).